RAD23B (RAD23 nucleotide excision repair protein B)
Description:
Multifunctional protein that participates in histone H4K20 demethylation, DNA repair, ubiquitin-dependent protein degradation and transcriptional regulation. Specifically demethylates mono-, di- and trimethylated 'Lys-20' of histone H4 (H4K20me1, H4K20me2, H4K20me3, respectively) into unmethylated forms. Activates the transcription of coding genes by demethylating H4K20me1 and the transcription of repetitive elements by demethylating H4K20me3. Multiubiquitin chain receptor involved in modulation of proteasomal degradation. Binds to polyubiquitin chains. Proposed to be capable to bind simultaneously to the 26S proteasome and to polyubiquitinated substrates and to deliver ubiquitinated proteins to the proteasome. May play a role in endoplasmic reticulum-associated degradation (ERAD) of misfolded glycoproteins by association with PNGase and delivering deglycosylated proteins to the proteasome. Involved in global genome nucleotide excision repair (GG-NER) by acting as component of the XPC complex, a nucleotide-excision repair complex that is involved in damage sensing during global genome nucleotide excision repair. In vitro, the XPC:RAD23B dimer is sufficient to initiate NER; it preferentially binds to cisplatin and UV-damaged double-stranded DNA. Recognizes a wide spectrum of damaged DNA characterized by distortions of the DNA helix including single-stranded loops, mismatched bubbles or single-stranded overhangs. Cooperatively with CETN2 appears to stabilize XPC.
Synonyms: HR23B; hHR23B; p58
Tractability: Small molecule: a structure with a bound ligand is known. PROTAC: ubiquitination databases record sites on it; its protein half-life has been measured.
Gene: Protein-coding gene on chromosome 9 (107,283,137 to 107,332,192, forward strand). Ensembl gene ENSG00000119318.
Subcellular location: Nucleus; Cytoplasm
Subcellular location (Human Protein Atlas): Nucleoplasm; Cytosol
Pathways (Reactome):
DNA Repair: DNA Damage Recognition in GG-NER; Formation of Incision Complex in GG-NER
Metabolism of proteins: Josephin domain DUBs; N-glycan trimming in the ER and Calnexin/Calreticulin cycle
Gene Ontology:
Molecular function: DNA damage sensor activity; histone H4K20 demethylase activity; polyubiquitin modification-dependent protein binding; protein binding; single-stranded DNA binding; damaged DNA binding; RNA polymerase II cis-regulatory region sequence-specific DNA binding; RNA polymerase II-specific DNA-binding transcription factor binding; transcription cis-regulatory region binding
Biological process: nucleotide-excision repair; regulation of proteasomal ubiquitin-dependent protein catabolic process; proteasome-mediated ubiquitin-dependent protein catabolic process; chromatin remodeling; embryonic organ development
Cellular component: cytoplasm; cytosol; nucleoplasm; nucleus; XPC complex
Genetic constraint (gnomAD): Loss-of-function variants: 4 observed, 40.89 expected, observed/expected ratio (o/e) 0.0978, 90% interval 0.047 to 0.22. The upper end of that interval is the gene's LOEUF score, 0.22, which puts it in group 1 of 6, group 1 being the genes least tolerant of losing a copy. Missense variants: 330 observed, 452.21 expected, observed/expected ratio (o/e) 0.73, 90% interval 0.67 to 0.8. Synonymous variants: 165 observed, 153.51 expected, observed/expected ratio (o/e) 1.07, 90% interval 0.95 to 1.22.
Homologues: Orthologues: chimpanzee RAD23B (99% identical), macaque RAD23B (99% identical), guinea pig RAD23B (95% identical), dog RAD23B (93% identical), rat Rad23b (91% identical), mouse Rad23b (91% identical), rabbit RAD23B (85% identical), pig RAD23B (78% identical), tropical clawed frog rad23b (76% identical), zebrafish rad23b (67% identical), Caenorhabditis elegans rad-23 (34% identical), Drosophila melanogaster CG10694 (26% identical). Paralogues in human: RAD23A (56% identical).